EGFR (epidermal growth factor receptor)
Diseases named in the same sentence as EGFR in open-access papers (continued):
Sharing a sentence is not in itself a finding about the gene and the disease.
tumor (continued). "The results indicated that the expression levels of the genes BCL2 and EGFR were significantly (p < 0.001) higher in normal tissue than in tumor tissue." (PMID 39202273, 2024). "In summary, this study has demonstrated that furmonertinib had good anti-tumor activity and tolerance in NSCLC patients with EGFR ex20ins mutation." (PMID 38651148, 2024). "Immune cells in the tumor microenvironment (TME) also play a key role in mediating EGFR-targeted therapy response." (PMID 40727266, 2024). "PROTAC canalso be used to target proteins that are involved in tumor growth,such as the androgen receptor and the EGFR." (PMID 38990186, 2024). "This conjugation also reduced tumor size in the xenograft EGFR-expressed human CRC tumors of nude mice." (PMID 39474040, 2024). "The extent of the research gap filled is that we have been able to validate the utility of CD44, EGFR, E-Cadherin, and vimentin as indicators of tumor aggressiveness and recurrence." (PMID 39050298, 2024). "Immunohistochemistry results demonstrated that levels of EGFR, Ki-67 (indicating tumor proliferation), and α-SMA (indicating angiogenesis) were decreased in the circ_0053943 depletion group and increased in the overexpression group." (PMID 38686044, 2024). "A high throughput immune-oncology screen identified EGFR TKI as potent enhancers of antigen-specific cytotoxic T-cell–mediated tumor cell killing." (PMID 39318388, 2024). "IL-6 blockade sensitized EGFR-mutant GEMM tumors to PD-1 inhibitors by increasing tumor-infiltrating IFNγ+ CD8+ T cells." (PMID 39015563, 2024). "Several tumors harboring genomic alterations with FDA-approved indications in other tumor types were found including pathogenic PIK3CA, EGFR Exon 19/20 insertions, KRAS G12C (N = 1), FGFR fusions (N = 1), BRAF V600E mutations (N = 4), and BRCA2 (N = 1)." (PMID 39191445, 2024). "EGFR immunohistochemistry of engrafted tumors revealed stronger EGFR-positive stains in the A253 tumor than in the MCF7 tumor." (PMID 38542206, 2024). "AG556 acts as an EGFR inhibitor and, although the role of 5-LO in tumor development and progression is not yet fully understood, combined EGFR and 5-LO inhibition was found to be beneficial." (PMID 39347835, 2024). "EGFR-amplified GSCs showed remarkable sensitivity to talazoparib treatment, which significantly suppressed tumor growth in EGFR-amplified subcutaneous models." (PMID 38473776, 2024). "EGFR pathway also plays an essential role in multiple tumor types, including breast, colorectal, cervical, and lung cancer." (PMID 38962426, 2024). "Forty-eight hours post UTMC treatment, EGFR protein expression in tumor tissue was assessed by Western blot and immunofluorescence." (PMID 38577322, 2024). "This modification aimed to achieve pH sensitivity, EGFR targeting, tumor penetration, endosomal escape, and localization to the nucleus and cytoplasm." (PMID 39482441, 2024). "Compared with cisplatin, the biparatopic anti-EGFR NDC enables efficient internalization into EGFR-positive cancer cells due to 4–5 fold higher tumor accumulation, thereby enhancing tumor-specific drug delivery while minimizing systemic distribution." (PMID 38566971, 2024). "In tumor cells, interleukin-6 (IL-6) signaling can lead to activation of the epidermal growth factor receptor (EGFR), which prolongs Stat3 activation." (PMID 39000275, 2024). "EGFRxHER2 T-BsAbs are also effectively ‘tumor monovalent’ when applied to EGFR+ or HER2+ single-positive tumors." (PMID 38650005, 2024). "In case NCCLu-027, the patient’s tumor was diagnosed as wild-type EGFR but showed a strong response to an EGFR inhibitor." (PMID 38398169, 2024).
tumor (continued). "The consequence of introducing EGFRvIII into cells that initially express WT EGFR is increased proliferation, angiogenesis and tumor invasion." (PMID 38339374, 2024). "Subsequent soft agar assay and corresponding statistics of average colony number also verified the suppressive effect of sh-EGFR or miR-7-5p mimic on the tumor-promoting activity of AFAP1-AS1." (PMID 39574469, 2024). "The EGFRxEGFR, HER2xHER2, and EGFRxHER2 T-BsAbs possess two tumor-specific Fabs that allow bivalent binding to EGFR+HER2+ double-positive PDAC tumors." (PMID 38650005, 2024). "This process increases the cross-presentation of tumor antigens to CD8+ T cells, leading to the expansion of EGFR-specific T cells and bolstering the immune response against tumor cells." (PMID 39192980, 2024). "used serial circulating tumor (ct)DNA to detect MAPK pathway alterations (SNV or indel in RAS/EGFR/BRAFV600 or MET or ERBB2 amplification) after various therapy lines." (PMID 39080202, 2024). "LCE-E and LCE-D demonstrated specific cellular binding properties on EGFR/PD-L1 double-positive tumor cells with higher affinity and improved maximum binding compared to the wildtype HCP-LCE." (PMID 38804304, 2024). "In a combined retrospective analysis, the predictive and prognostic value of primary tumor localization in the treatment of patients with anti-EGFR therapy, cetuximab, and panitumumab, was evaluated." (PMID 39202071, 2024). "Dual inhibition of MET and VEGF combined with EGFR TKIs markedly restrained tumor growth in both human NSCLC xenograft models and in an EGFR/MET co-altered case." (PMID 39354638, 2024). "These BiKEs successfully stimulated EGFR-positive tumor cell killing and IFN-γ and TNF-α secretion by NK cells." (PMID 39339180, 2024). "The highly tumor-specific antibody–drug combination depatuxizumab-mafodotin (depatux-m) targets EGFR via a monoclonal antibody coupled to a cytotoxin." (PMID 39456611, 2024). "This includes investigating novel pathways contributing to tumor growth and survival beyond commonly targeted pathways, such as EGFR and MAPK." (PMID 38655092, 2024). "Unfortunately, while most EGFR-mutant NSCLCs initially respond to EGFR-TKIs, they ultimately become resistant resulting in tumor relapse." (PMID 38177097, 2024). "Co-targeting these kinases is a rational approach to break tumor cell tolerance, either by using inhibitors with a wilder specificity (e.g., afatinib) or a combination of inhibitors (e.g., EGFR TKI plus crizotinib)." (PMID 39041204, 2024). "Overall, these results demonstrated that dual targeting of B7H3 and EGFR significantly enhanced the susceptibility to OXP and delayed tumor growth in CRC." (PMID 38370387, 2024). "This combination is now FDA-approved for treating metastatic or recurrent NSCLC as a first-line treatment, excluding those with EGFR or ALK genomic tumor aberrations." (PMID 39410008, 2024). "Overall, the data indicated that As2O3 targets the EGFR signaling pathway to inhibit both tumor growth and the development of drug resistance in gefitinib-resistant NSCLC cells." (PMID 39717738, 2024). "Upon ligand binding, EGFR activation stimulates Treg activation, creating an immunosuppressive microenvironment that promotes tumor growth." (PMID 38191508, 2024). "Univariate analysis by the Cox regression model found that several clinicopathological parameters were associated with survival outcome in COAD patients, including pT stage, pN stage, LVI, PNI, postoperative chemotherapy and tumor EGFR." (PMID 38370387, 2024). "Tumor diameter, MWA power (High), tumor differentiation (Poor), EGFR mutations, and SIRI (High) were independent related factors for DFS (HR 2.214, P<0.001; HR 0.500, P=0.005; HR 3.604, P<0.001; HR 0.144, P<0.001 and HR 2.391, P<0.001, respectively)." (PMID 38571504, 2024). "Exposure to mild ROS levels induced an aberrant phosphorylation pattern and impaired EGFR trafficking and degradation, leading to ROS-mediated tumor progression." (PMID 39001381, 2024).
tumor (continued). "A few reports indicate that EGFR is immunologically “cold”, and that the tumor microenvironment (TME) is unfavorable to ICI therapy." (PMID 39280252, 2024). "In a preclinical study, the combination of amivantamab and lazertinib, which targets both the EGFR extracellular and catalytic domains, demonstrated synergistic tumor growth inhibition." (PMID 38474400, 2024). "The DTT-EG vaccine, which specifically targets EGFR, holds promise for achieving long-term tumor control in these patients following surgical intervention." (PMID 39766327, 2024). "The resulting GE11-Exo-let-7a miRNA demonstrated a high affinity for EGFR-overexpressing cancer cells and significantly reduced tumor growth, highlighting the potential of GE11-modified exosomes as an effective delivery system for targeted EGFR therapy." (PMID 39204374, 2024). "EGFR, known for its significance in tumor proliferation and viability, is effectively controlled by LRIG1." (PMID 38790164, 2024). "In vivo, EGFR siRNA LPX + UTMC reduced tumor EGFR expression by ~30% and significantly inhibited tumor growth by day 9 (~40% decrease in tumor volume vs. NC siRNA LPX + UTMC, p<0.05)." (PMID 38577322, 2024). "Osimertinib has high anti-tumor activity in two human-derived tissue xenograft models containing EGFR ex20ins (M766_A767in&ASV and H773_V774ins NPH) with a wide therapeutic window." (PMID 38774882, 2024). "In our previous study, we demonstrated that HOXD3 was upregulated in HCC and promoted tumour metastasis by inducing the expression of EGFR and ITGA2 in HCC cells and tissues, indicating that HOXD3 is a crucial angiogenic factor in HCC." (PMID 38493218, 2024). "In tumor cells, IL-6-induced activation of Stat3 was increased or maintained by activation of the epidermal growth factor receptor (EGFR)." (PMID 39000275, 2024). "Inhibiting IL-6 also increased NK- and T cell-mediated killing of human osimertinib-resistant EGFR-mutant NSCLC tumor cells in cell culture." (PMID 39015563, 2024). "The suppressive function of Tregs is enhanced by ILC2s production of AREG protein, promoting EGFR-expressing tumor progression." (PMID 39309440, 2024). "SW1990 tumor-bearing mice were given one infusion of human T cells and treated with 10ug EGFR, HER2, and EGFRxHER2 T-BsAbs every 3–4 days until tumors were harvested 10 days after the start of treatment." (PMID 38650005, 2024). "Tumor‐derived exosomal circRNAs have been reported to be key circRNA in the process of EGFR‐TKIs resistance." (PMID 39247621, 2024). "Epidermal Growth Factor Receptor (EGFR) and its family members have a regulatory role in tumor proliferation." (PMID 39155844, 2024). "By inhibiting only one genetic driver—for example, EGFR—only cells harbouring alterations in EGFR will be targeted, while the other tumour cells remain unaffected, leading to sub-clonal selection and, eventually, to recurrence." (PMID 39272879, 2024). "Previous studies have attempted to detect EGFR mutations in patients with NSCLC using radiomics, specific tumor markers, and morphological features via traditional CT scans." (PMID 38679659, 2024). "Combined treatment with GHRH-R antagonist and EGFR inhibitor significantly extended tumour doubling time from 9.12+/−1.01 days to 14.97+/−1.5 days and provoked a 57.5% decrease in tumour weight as compared to controls." (PMID 39456984, 2024). "Over 50% of GBM tumors overexpress EGFR, a protein involved in tumor progression and drug resistance." (PMID 39001381, 2024). "When this delivery system was paired with an EGFR-targeting peptide, high tumor penetrance and increased overall survival were observed in vitro and in vivo." (PMID 38396993, 2024). "elegantly demonstrated that expressing an EGFR TCE from an EGFRvIII CAR-T enhanced anti-tumor efficacy while improving safety." (PMID 39606234, 2024). "Collectively, FKC inhibits glucose metabolism and tumor angiogenesis in NPC by targeting the HSP90B1/EGFR/PI3K/Akt/mTOR signaling axis." (PMID 38711062, 2024).
tumor (continued). "Lapatinib is a dual tyrosine kinase inhibitor that can inhibit the proliferation and activity of tumor cells by simultaneously acting on the epidermal growth factor receptor (EGFR) and human epidermal growth factor receptor 2 (HER-2)." (PMID 39507529, 2024). "We have previously demonstrated that LDOC1 functions as a tumor suppressor gene in two EGFR-driven cancers: oral squamous cell carcinoma and NSCLC." (PMID 38338651, 2024). "Through the combination of ICO15K-cBiTE AdV, which encodes an EGFR-targeting BiTE, with FR-α-specific CAR T cells, the objective of this study was to address the issue of tumor heterogeneity and the potential loss of tumor antigens." (PMID 38464532, 2024). "ARAF amplification potentially fosters conditions that promote tumor cell survival and neuroendocrine marker transcription under EGFR-TKIs." (PMID 39456595, 2024). "The preclinical studies showed that the half-maximal inhibitory concentration (IC50) of furmonertinib for EGFR ex20ins type was 5-10 times lower than that of EGFR wild, which indicates furmonertinib has shown encouraging anti-tumor activity in EGFR 20ins." (PMID 38651148, 2024). "MRTX1133 showed synthetic lethality with EGFR inhibition in colorectal cancer and synergistic anti-tumor effects in PDAC." (PMID 38607041, 2024). "The epidermal growth factor receptor (EGFR) is a linchpin in tumor progression and presents a potential therapeutic target in MIBC." (PMID 38868531, 2024). "By activating EGFR and coupling with intercellular signaling proteins, numerous tumor-related signaling pathways, such as RAS, AKT, and STAT3, are involved in tumor progression." (PMID 38831321, 2024). "Among the 24 patients who tested positive for EGFR-TK, the assessment of tumor expression revealed three (12.5%) with low expression, 13 (54.2%) with moderate expression, and eight (33.3%) with strong expression." (PMID 39429333, 2024). "One of the mechanisms for tumor cell-stimulated expression of PD-L1 is the activation of EGFR, PI3K/mTOR, or MAPK signaling pathways." (PMID 39113885, 2024). "αEGFR-E-P125A reduces VM, angiogenesis, tumor growth, and metastasis by inhibiting EGFR and α5β1 integrin signaling, and is a promising therapeutic agent for TNBC treatment, used alone or in combination with chemotherapy." (PMID 38315147, 2024). "EGFR mutations (Q1067G, R1068G) close to the PDZ binding motif (1037–1065) have been identified in tumour samples." (PMID 38604999, 2024). "The EGFR is considered one of the important protein targets in the development of anticancer drugs and therefore, the inhibition of EGFR is essential for the treatment of cancer to inhibit the progression and growth of EGFR-expressing tumor cells." (PMID 38266021, 2024). "EGFR can activate downstream signaling pathways, thereby promoting tumor cell proliferation, migration, and invasion through ligand binding." (PMID 38253629, 2024). "WBP2 is an emerging tumor protein that functions in different oncogenic signaling pathways, such as the ER/PR, EGFR, PI3K, Hippo, and Wnt signaling pathways, and WBP2 has gained attention as a potential drug target." (PMID 38239300, 2024). "Tumor-derived exosomes deliver EGFR effectively to DCs and macrophages to suppress innate immunity and promote tumor progression." (PMID 38495881, 2024). "Gefitinib (GEF) acts reversibly on wild-type and certain mutant EGFRs and inhibits the autologous phosphorylation of EGFR tyrosine, thereby further inhibiting downstream signaling and promoting tumor metastasis." (PMID 38983928, 2024). "EMT, recognized as a driving force behind tumor progression, leads to both innate and acquired resistance to EGFR tyrosine kinase inhibitor (TKI) treatment." (PMID 39375945, 2024). "Anti-EGFR monoclonal antibodies not only have the ability to directly kill tumor cells but also possess immune-modulatory properties." (PMID 38809459, 2024). "TCO-labeled GE11 peptide bound to EGFR on the surface of A431 tumor cells and was used for the iEDDA reaction." (PMID 38675140, 2024).
tumor (continued). "Recently reported ARCAD studies have shown a strong correlation between tumor shrinkage and prognosis in combination chemotherapy with anti-EGFR mAb13." (PMID 39587053, 2024). "Overexpression and mutations of EGFR have been found in patients with NSCLC, therefore, tumor cell proliferation can be effectively inhibited by counteracting EGFR expression." (PMID 38983928, 2024). "For example, the regulatory factor CRNDE regulates the EGFR gene to regulate invasion of cells, invasion of tumor, and microtubule dynamics." (PMID 38711992, 2024). "The results revealed that patients harboring EGFR mutations exhibit increased levels of sEV PD-L1 in circulation, which inversely correlated with the presence of CD8+ T cells in tumor tissues." (PMID 39062533, 2024). "EGFR can mediate oncogenic signals involved in the proliferation and survival of tumor cells and is expressed and activated in a variety of epithelial malignancies." (PMID 38730287, 2024). "In fifty percent of the tumours with EGFR amplification, activating EGFR gene rearrangements occur, with the most common extracellular domain mutation being EGFRvIII." (PMID 39272879, 2024). "Activation of the EGFR pathway has been demonstrated to enhance the growth, invasion, and angiogenesis of tumor cells." (PMID 38576484, 2024). "EGFR amplification occurs mostly in the infiltrating edges of tumors and is considered to play a role in gliomagenesis and tumor invasiveness." (PMID 39518074, 2024). "In advanced NSCLC, ctDNA detection has been limited to patients who have either progressed on EGFR TKIs or have inadequate tumor tissue for molecular analysis." (PMID 39066920, 2024). "In OSCC tumor tissues with high EGFR expression, Nimotuzumab-ICG showed a higher fluorescence imaging signal and better image contrast than images of tumors with low or no EGFR expression." (PMID 39183296, 2024). "For improving the efficacy of EGFRvIII-targeting CAR-T without inducing off-targeting toxicity, a humanised antibody M27 was developed to specifically bind to both wild-type EGFR- and EGFRvIII-overexpressing tumour cells." (PMID 38660136, 2024). "Other markers, such as EGFR amplification and TERT promoter mutations, are linked to more aggressive tumor behavior and shorter survival times." (PMID 39767571, 2024). "In humans, IL-1β release after exposure to air pollutants reprograms lung epithelial cells with pre-existing EGFR mutations into a progenitor-like state with active JAK-STAT signaling and tumor growth." (PMID 39636982, 2024). "Ablation of KDM3A, KLF5, SMAD4, or EGFR elevates the population of tumor-infiltrating T cells and dendritic cells and decreases myeloid cell infiltration." (PMID 39519018, 2024). "Our data provide more evidence to consider KCa3.1 channels as a therapeutic target in NSCLC, especially in advanced stages of tumor spreading and EGFR-TKI resistance." (PMID 38177097, 2024). "Anti-EGFR antibodies also induce antibody-dependent cellular cytotoxicity, facilitating immune cell cross-talk, allowing for tumor-antigen-specific cellular immunity and the development of antigen-specific T-lymphocyte responses." (PMID 39559603, 2024). "Cholinergic nerves activate the epidermal growth factor receptor (EGFR) and its associated signaling pathways through cholinergic receptors, including nicotinic and muscarinic types, thus stimulating tumor cell growth." (PMID 38567163, 2024). "Our evidence strongly suggests that C0epi is the tumor-initiating cluster (START) that contributes to EGFR T790M/L858R pulmonary tumors." (PMID 38546390, 2024).